KLF14 (KLF transcription factor 14)
Diseases named in the same sentence as KLF14 in open-access papers (continued):
Sharing a sentence is not in itself a finding about the gene and the disease.
atherosclerosis (continued). "It has been shown that perhexiline, a small drug that is approved for clinical use in many countries except the United States, to treat angina and heart failure, can effectively induce KLF14 expression in the liver while reducing atherosclerosis in ApoE-null mice." (PMID 32548128, 2020). "Recent findings showing the role of KLF14 in chronic inflammatory responses and the pathogenesis of atherosclerosis may be particularly relevant to this finding." (PMID 29466246, 2018). "However, the exact mechanism of the KLF14 gene regulation of lipid metabolism and its associated impacts on atherosclerosis is not well elaborated." (PMID 36837818, 2023). "Upregulation of hepatic Klf14 expression may thus protect against atherosclerosis." (PMID 29942807, 2018). "KLF14 further contributes to lipid metabolism regulation by enhancing cholesterol efflux via ABCA1, highlighting the multifaceted involvement of KLFs in atherosclerosis pathogenesis." (PMID 41373858, 2025). "KLF14 and the MAPK-signaling pathway are also closely correlated with the expression of inflammatory factors in oxidative adaptation in prostate cancer and atherosclerosis." (PMID 38143751, 2023). "Furthermore, studies have found that the cardiovascular drug perhexiline can induce the expression of KLF14 and increase blood HDL-C levels and cholesterol outflow ability by upregulating ApoA1 and ameliorating the development of atherosclerosis by targeting the KLF14 pathway." (PMID 34983946, 2022).
Insulin resistance (16 papers, 2013 to 2025). Increased resistance towards insulin, that is, diminished effectiveness of insulin in reducing blood glucose levels. "In adipose tissue, KLF14 gene expression has been associated with combined insulin resistance characterized by elevated levels of TGs and fasting insulin and decreased level of HDL-C." (PMID 36837818, 2023). "The risk C allele of KLF14 rs4731702 is associated with insulin resistance, which increases the risk of T2DM." (PMID 37351102, 2023). "Variations of KLF14 are associated with body shape indices, metabolic traits, insulin resistance, and metabolically healthy status." (PMID 35456983, 2022). "Genome-wide association studies (GWASs) have identified KLF14 variants to be associated with a multitude of metabolic pathologies, such as insulin resistance (IR), diabetes mellitus, coronary artery disease, ischemic stroke, and myocardial infarction." (PMID 35456983, 2022). "Female KLF14‐KO mice exhibited greater adiposity, insulin resistance, elevated serum triglyceride levels, and fat storage shifts to the visceral depots from the subcutaneous fat depots." (PMID 40790397, 2025). "We found broad as well as sex‐biased protection from weight gain, adiposity, and insulin resistance in our model of KLF14 overexpression." (PMID 40790397, 2025). "We further investigated the effect of KLF14 overexpression on adiposity, insulin resistance, serum lipid profiles, and gene expression in KLF14Tg mice." (PMID 40790397, 2025). "Another possibility for the altered KLF14 expression is insulin resistance, which downregulates the normal expression of KLF14." (PMID 37351102, 2023). "KLF14 C-carrier genotypes had a significant impact on insulin resistance compared to the TT genotype." (PMID 37351102, 2023). "Several such studies have implicated the transcription factor KLF14, a member of the Krüpple-like factor family (KLF), in the development of metabolic diseases, including obesity, insulin resistance, and T2D." (PMID 32548128, 2020). "As KLF14 is an insulin-sensitizing transcription factor, the C/C genotype of rs4731702 in diabetic patients shows significant insulin resistance and, in the future, is more prone to develop critical pathologies regarding altered lipoproteins profile such as severe CADs." (PMID 36837818, 2023). "Numerous studies have demonstrated that in non-diabetic individuals, the risk alleles of KLF14 genes for T2DM are associated with insulin resistance characterized by increased fasting insulin." (PMID 36837818, 2023). "Given the opposite functions of Insulin on hepatic fatty acid oxidation and its influence on PGC-1α signaling, this possibly suggests that KLF14 might have some role to play in insulin resistance." (PMID 36902112, 2023). "Several genetic variants of the KLF14 gene on chromosome 7 have been reported to be associated with metabolic diseases such as obesity, T2DM, insulin resistance, and cardiovascular disorders, with a gender bias, showing stronger association in females as compared to males." (PMID 35455702, 2022). "Variants within this cluster mapped to genes with known effects on insulin resistance, including IGF2, INSR, KLF14, and PPARG in adipose tissue." (PMID 38200577, 2024). "KLF10 and KLF14, which are upregulated in response to high-fat diet, promoted PGC-1α-induced hepatic gluconeogenesis, supporting their possible role in insulin resistance." (PMID 36902112, 2023). "In female mice but not male mice, adipocyte‐specific KLF14 depletion resulted in insulin resistance, increased adiposity, and fat redistribution from subcutaneous to visceral adipose tissues, characteristic of abdominal obesity." (PMID 40790397, 2025). "Exploring this transcription factor’s metabolic role on the function of HDL-C and insulin resistance in female mice was positive, but the results showed that the metabolic phenotypes of male mice were not affected by KLF14." (PMID 35238325, 2022).
Obesity (16 papers, 2013 to 2025). Accumulation of substantial excess body fat. "KLF14 is strongly associated with the expression of multiple metabolic traits, such as diabetes and obesity." (PMID 37351102, 2023). "We further revealed the interactive effect of obesity on the association between KLF14 variants and body shape indices." (PMID 35456983, 2022). "Taken together, our data revealed that variations of the KLF14 gene, including gene variants and methylation levels for body shape indices, IR status, and metabolic traits, are highly dependent on age, sex, or obesity." (PMID 35456983, 2022). "In subgroup analysis, the association between KLF14 variants and body shape indices occurred only in obese women, showing the critical role of both sex and obesity in associations between KLF14 variants and body shape indices." (PMID 35456983, 2022). "Global Klf14 loss of function studies in mice have demonstrated mixed findings with regards to its role in obesity and metabolism, with two separate studies demonstrating inconsistent phenotypes on adiposity and glucose tolerance." (PMID 33397965, 2021). "Human KLF14 controls many essential genes that are linked to a range of metabolic conditions including obesity, cholesterol, insulin and glucose levels." (PMID 23557393, 2013). "In addition, environmental and physiological factors such as diet, age, gender, and obesity are also responsible for genetic mutations in KLF14." (PMID 36837818, 2023). "This study investigated whether age, sex, and obesity mediate the effects of KLF14 variants and DNA methylation status on body shape indices and metabolic traits." (PMID 35456983, 2022). "Thus, the potential interactive effect of sex and obesity on the association between KLF14 variants and cardiometabolic phenotypes required further elucidation." (PMID 35456983, 2022). "Since KLF14 is typically linked to the regulation of gene expressions in adipose tissues, the association of its polymorphic variations with obesity or PCOS might be of significance in disease pathology." (PMID 35455702, 2022). "Finally, we demonstrate that deletion of Trim28 leads to loss of expression of the gene Klf14, a well-described sex-specific metabolic regulator, revealing a previously unexplored link between Trim28, Klf14, and the development of obesity." (PMID 33397965, 2021). "Distribution of KLF14 genotypes and allelic frequencies in diseased population, in accordance with age, gender, obesity, and smoking." (PMID 37351102, 2023). "An investigational study on mice models has evidenced that aging and obesity can down-regulate KLF14 expression." (PMID 36837818, 2023). "It is not clear why there are discrepancies among the three studies which observed different effects of high-fat feeding and obesity on liver Klf14 levels, fasting glucose, and the formation of atherosclerotic plaque." (PMID 32548128, 2020). "In the obesity study, strong genetic control of body fat set-point as well as microbiome plasticity was unraveled, and multiple genetic loci were identified for obesity traits and dietary responses (e.g., Sptlc3, Klf14, Degs1, Npc, Cbr1, and amylases)." (PMID 26202330, 2015). "Recently, human KLF14 has been identified as a regulator linking obesity to the T2D; KLF14 acts as a master trans-regulator of adipose gene expression in T2D and HDL-cholesterol associated cis-acting eQTL." (PMID 23557393, 2013). "For example, NKX6.1 is essential for both early and late stages of pancreatic development with a critical role in the formation of β cells, KLF14 is an important regulator of metabolic diseases, such as diabetes and obesity, and E2F3 activates β-cell proliferation." (PMID 36899442, 2023). "Differential genetic and epigenetic effects of KLF14 are age-, sex- and obesity-dependent." (PMID 35456983, 2022). "Furthermore, KLF14 has recently emerged as a master regulator of multiple metabolic phenotypes in adipose tissue, and it is closely correlated with type 2 diabetes and obesity." (PMID 34031939, 2021).
Obesity (continued). "Thus KLF14 acts as a master switch controlling processes that link changes in the behavior of subcutaneous fat to disorder in muscle and liver that contributes to diabetes, obesity and other conditions." (PMID 23557393, 2013). "The effect of KLF14 is reportedly not driven by obesity, quite unlike the known BMI- and fat mass mediated effect of FTO via insulin resistance." (PMID 24098730, 2013).
colorectal cancer (13 papers, 2015 to 2024). A primary or metastatic malignant neoplasm that affects the colon or rectum. "The possible mechanism underlying KLF14 downregulation in colorectal cancer cells is based on the interaction occurring between circTADA2A and its target miR-374a-3p." (PMID 36077352, 2022). "CircTADA2A was shown to regulate Kruppel like factor 14 (KLF14) via binding to miR-374a-3p, and then suppress colorectal cancer progression." (PMID 38635778, 2024). "This miRNA can target KLF14; therefore, HAND2-AS1 suppresses progression of colorectal cancer via enhancing KLF14 expression." (PMID 37204522, 2023). "A study on KLF14’s role in the suppression of colorectal cancer revealed that increased expression of KLF14 induces apoptosis in cancerous cells." (PMID 36837818, 2023). "Recent studies revealed that KLF14 was downregulated in colorectal cancer, breast cancer, lymphoma, cervical cancer, cancer of the floor of the mouth, and pancreatic cancer." (PMID 38143751, 2023). "KLF14 can inhibit cancer in colorectal cancer, breast cancer, hepatocellular carcinoma, and other tumors." (PMID 38143751, 2023). "Another study has found that KLF14 suppressed the progression of colorectal cancer by targeting the HAND2-AS1/miR-1275 axis." (PMID 36837818, 2023). "LncRNA HAND2‐AS1 suppresses colorectal cancer progression by sponging miR‐1275 to modulate KLF14 expression." (PMID 32767514, 2020). "A tissue microarray of stage I-III colorectal cancer (CRC) patient samples revealed that Krüppel-like transcription factor 14 (KLF14) expression was downregulated in CRC samples and the low KLF14 expression correlated with advanced tumor stage and size." (PMID 31146503, 2019). "However, circTADA2A binds to miR‐374a‐3p, functioning as a ceRNA to regulate target KLF14 and inhibit tumor proliferation in colorectal cancer." (PMID 39428538, 2024). "KLF14 repressed the growth of colorectal cancer by interacting with miR-374a-3p." (PMID 36837818, 2023). "Notably, additional studies have identified KLF14 as a tumor suppressor in the development and progression of colorectal cancer." (PMID 34983946, 2022). "Moreover, recently reported findings revealed that the transcription factor KLF14 participates in antineoplastic effects during the development of colorectal cancer (CRC) by regulating the glycolytic enzyme LDHB, which confirmed the regulatory effect of KLF14 on glycolysis." (PMID 34983946, 2022).
diabetes (13 papers, 2013 to 2024). "TCF7L2 is associated with diabetes and exhibits dependence on KLF-14, where reduced expression increases pre-adipocyte proliferation but impairs lipogenesis." (PMID 38672763, 2024). "These include CCND2, CILP2, PBX4, SH2B3, SLC6A4, TCF7 and KLF14, which have polymorphisms associated with diabetes risk." (PMID 27029739, 2016). "As diabetes is a condition linked to increased cardiovascular risk, it was unsurprising that our work revealed gene interaction between KLFs, particularly KLF-14, and genes associated with diabetic risk factors, such as CAMK1D, HHEX, JAZF1, and TCF7L2." (PMID 38672763, 2024). "Notably, TCF7L2′s ability to modulate PIK3R1 expression suggests its involvement in insulin signaling pathways, potentially mediating diabetes risk through interactions with KLF-14." (PMID 38672763, 2024). "Although a strong association between the KLF14 gene polymorphism and both diabetes mellitus and cardiac problems has been found, the exact mechanisms by which it affects these conditions are still unknown." (PMID 37351102, 2023). "However, a significant risk association was found between diabetes mellitus and the KLF14 rs4731702 polymorphism in women compared to men." (PMID 37351102, 2023). "Some studies have suggested that the KLF14 gene polymorphism may interact with other genetic and environmental factors to increase the risk of both diabetes mellitus and cardiac problems." (PMID 37351102, 2023). "Several kinds of metabolic disorders, including diabetes mellitus (DM), cardiovascular diseases (CVDs), and especially coronary artery diseases (CADs), are strongly linked with the variants near the KLF14 gene which is located on chromosome 7." (PMID 36837818, 2023). "In conclusion, KLF14 C carrier genotypes may increase the risk of diabetes pathogenesis." (PMID 37351102, 2023). "In addition, the age-related DNA methylation level of KLF14 may be a risk marker for diabetes mellitus." (PMID 35456983, 2022). "Our list is supported by colocalization of genes known to lead to Mendelian forms of diabetes (e.g., SLC2A2 and WFS1) and of genes with previously demonstrated mechanisms of association with IR/T2D (e.g., METAP2, PLEKHA1 [TAPP1], FAM13A, and KLF14)." (PMID 35292083, 2022). "In addition, methylation of KLF14, FHL2 and GNPNAT1 was associated with lower diabetes risk in the Botnia prospective study." (PMID 27029739, 2016).
breast carcinoma (9 papers, 2015 to 2024). "For T2D and breast cancer susceptible groups with the KLF-14- rs972283 variant association found to be weak among European and African population." (PMID 36831624, 2023). "In the recessive inheritance model, there is a strong correlation between the KLF14 (GG + GA) and KLF14-AA genotypes that increases breast cancer susceptibility OR = 3.17 (CI = 1.6507–6.1076), RR = 1.94 (CI = 1.2618–2.9971), and p < 0.0005." (PMID 36831624, 2023). "In the dominant inheritance model, there is a significant association between the KLF14-GG and KLF14-(GA + AA) genotypes and leads to increased breast cancer susceptibility with OR = 1.87 (CI = 1.07–3.26), RR = 1.87 (CI = 1.0465–1.7336), and p < 0.026." (PMID 36831624, 2023). "KLF14 and the KLF-14 (rs972283 A > G) roles in the breast cancer development remain to be investigated in future studies." (PMID 36831624, 2023). "KLF14 suppressed breast cancer cell invasion and M2 macrophage polarization through modulating SOCS3/RhoA/Rock/STAT3 signaling." (PMID 38143751, 2023). "Previous research studies have not extensively elucidated the correlation of genotypes and allele variations of the PI3K, AKT-1, KLF-14, MDM4 and miRNAs 27a, miR-196a genes with the predisposition of Breast cancer in Saudi Arabia." (PMID 36831624, 2023). "In breast cancer, it has been demonstrated that the polarisation of M2 macrophage was modulated by KLF14 via SOCS3/RhoA/ROCK signalling pathway, thereby suppressing tumour growth." (PMID 36178087, 2022). "Overexpression of KLF14 significantly reduced breast cancer cell proliferation and invasion." (PMID 39518098, 2024). "While the KLF14-GA genotype was not linked to breast cancer susceptibility, with an OR = 1.31 (CI = 0.7171–2.4004), RR = 1.12 (CI = 0.8681–1.4554), and p < 0.37." (PMID 36831624, 2023). "Furthermore, the hypermethylation level of KLF14 was correlated to its downregulation in breast cancer cells." (PMID 37551728, 2023). "The Krüpple-like Transcription Factor KLF-14 rs972283 G SNP was not related to age status in BC (p = 0.83); however, a strong association was reported with respect to breast cancer staging (p = 0.006)." (PMID 36831624, 2023). "Moreover, RAP1A-RADIL inside-out signaling which is essential for breast cancer cell migration and invasion, can be inhibited by KLF14 through binding to C-terminal PDZ domain of RADIL and restricting RADIL from interacting with activated RAP1A spatially." (PMID 31448237, 2019). "Also it was suggested that the KLF14/miR-1283/TFAP2C axis inhibited HER2+ breast cancer progression, which might provide novel insight into mechanical exploration for this disease." (PMID 36831624, 2023). "In addition, KLF14 has been reported to be associated with HCC and breast cancer." (PMID 35570248, 2022). "KLF14 binds to the miR-1283 promotor and enhances expression to inhibit the progression of HER2+ breast cancer." (PMID 38143751, 2023).